NEK9 (NIMA related kinase 9)
Description:
Pleiotropic regulator of mitotic progression, participating in the control of spindle dynamics and chromosome separation. Phosphorylates different histones, myelin basic protein, beta-casein, and BICD2. Phosphorylates histone H3 on serine and threonine residues and beta-casein on serine residues. Important for G1/S transition and S phase progression. Phosphorylates NEK6 and NEK7 and stimulates their activity by releasing the autoinhibitory functions of Tyr-108 and Tyr-97 respectively.
Synonyms: Nek8; NERCC; DKFZp434D0935; MGC16714; NERCC1; APUG; LCCS10; NC
Tractability: Small molecule: a high-quality ligand is known; it belongs to a druggable protein family. PROTAC: it is named in the literature on targeted protein degradation; ubiquitination databases record sites on it; its protein half-life has been measured; a small molecule that binds it is known.
Target class: Other protein kinase NEK family; Kinase; Enzyme; Other protein kinase group; Protein Kinase
Gene: Protein-coding gene on chromosome 14 (75,079,353 to 75,127,344, reverse strand). Ensembl gene ENSG00000119638.
Subcellular location: Cytoplasm; Nucleus
Pathways (Reactome):
Cell Cycle: Activation of NIMA Kinases NEK9, NEK6, NEK7; EML4 and NUDC in mitotic spindle formation; Nuclear Pore Complex (NPC) Disassembly
Gene Ontology:
Molecular function: protein binding; protein kinase activator activity; protein kinase binding; protein serine kinase activity; protein serine/threonine kinase activity; ATP binding; protein kinase activity
Biological process: mitotic cell cycle; regulation of mitotic cell cycle
Cellular component: centrosome; cytoplasm; nucleus; cytosol
Genetic constraint (gnomAD): Loss-of-function variants: 56 observed, 83.57 expected, observed/expected ratio (o/e) 0.67, 90% interval 0.54 to 0.84. The upper end of that interval is the gene's LOEUF score, 0.84, which puts it in group 3 of 6, group 1 being the genes least tolerant of losing a copy. Missense variants: 788 observed, 976.61 expected, observed/expected ratio (o/e) 0.81, 90% interval 0.76 to 0.86. Synonymous variants: 352 observed, 373 expected, observed/expected ratio (o/e) 0.94, 90% interval 0.86 to 1.03.
Homologues: Orthologues: chimpanzee NEK9 (99% identical), macaque NEK9 (99% identical), dog NEK9 (97% identical), rabbit NEK9 (97% identical), guinea pig NEK9 (96% identical), rat Nek9 (96% identical), pig NEK9 (96% identical), mouse Nek9 (96% identical), tropical clawed frog nek9 (70% identical), Drosophila melanogaster niki (25% identical). Paralogues in human: NEK8 (22% identical), NEK3 (15% identical), NEK5 (15% identical), NEK11 (15% identical), NEK10 (14% identical), NEK2 (12% identical), NEK7 (11% identical), NEK6 (11% identical).
Diseases named in the same sentence as NEK9 in open-access papers:
NEK9 is named in the same sentence as 37 diseases in open-access papers, as found by Europe PMC text mining. Sharing a sentence is not in itself a finding about the gene and the disease. The quoted sentences say what the papers report.
gastric cancer (6 papers, 2021 to 2025). A primary or metastatic malignant neoplasm involving the stomach. "In essence, these authors showed that Nek9 can influence RhoA activation and enhance cellular motility in gastric cancer via this phosphorylation event." (PMID 35409400, 2022). "Furthermore, NEK9 inhibitors have shown potential in halting metastatic processes in gastric cancer." (PMID 41154634, 2025). "The ability of NEK9 to phosphorylate ARHGEF2 enhances its activity, leading to increased cell motility and metastatic potential in gastric cancer cells." (PMID 41154634, 2025). "In gastric cancer specifically, SLIT2 promotes metastasis by activating the kinase NEK9." (PMID 40461943, 2025). "Formation of the NEK9-ROBO1-SLIT2 ternary complex promoted NEK9-mediated phosphorylation of the transcriptional elongation factors, tripartite motif containing 28 (TRIM28) and cortactin (CTTN), which helped to promote metastasis in gastric cancer cells." (PMID 41154634, 2025). "Consistently, NEK9 expression is significantly higher in gastric cancer compared to their noncancerous counterparts, as shown by immunohistochemistry (IHC) analysis." (PMID 41154634, 2025). "Together, these findings suggest that NEK9 may be an attractive therapeutic target for slowing or even halting the spread of certain cancers harboring EML4–ALK fusions, especially gastric cancer or NSCLC." (PMID 41154634, 2025). "Likewise, activation of NEK9 (and NEK7) promoted the activation of oncogenic EML4–ALKv3 and V5 fusion proteins that are involved in the progression of certain cancers, including non-small cell lung cancer (NSCLC) and gastric cancer." (PMID 41154634, 2025).
breast carcinoma (4 papers, 2021 to 2025). "It is evident that lncRNA ATB and Nek9 are expressed at high levels in breast cancer patients and are positively correlated with the occurrence and development of the disease." (PMID 35935324, 2022). "For example, NEK2 has an important role in centrosome separation and is implicated in breast cancer progression, while NEK6, NEK7 and NEK9 are involved in mitotic spindle assembly, which requires regulation of microtubule polymerization." (PMID 36550548, 2022). "The expression of lncRNA ATB and Nek9 is closely associated with lymph node metastasis and TNM stage in breast cancer patients (P < 0.05)." (PMID 35935324, 2022). "Up-regulation of PLK1 in some of the breast cancer subtypes may inhibit tumor development by interfering with cytokinesis and mitosis as well as one of the NIMA kinases NEK9, which is associated with tumor growth prevention, when upregulated." (PMID 40724805, 2025). "Besides, the Spearman correlation coefficient shows that lncRNA ATB and Nek9 are positively correlated with breast cancer incidence (P < 0.05)." (PMID 35935324, 2022). "The experimental results reveal that lncRNA ATB and Nek9 are highly expressed in breast cancer patients, are significantly associated with lymphatic metastasis and TNM staging of breast cancer, and promote the development of breast cancer." (PMID 35935324, 2022). "Therefore, the levels of lncRNA ATB and Nek9 in patients with breast cancer were detected by Q-PCR, and their relationship with disease development was analyzed." (PMID 35935324, 2022). "Therefore, it is necessary to use real-time fluorescence quantitative PCR (Q-PCR) to detect the expression of lncRNA ATB and Nek9 in breast cancer patients and further analyze the expression of these two markers in breast cancer patients." (PMID 35935324, 2022). "However, there are relatively few clinical studies on the pathogenesis of lncRNA ATB and Nek9 in breast cancer." (PMID 35935324, 2022). "In addition, some scholars pointed out that Nek2 and Nek9 jointly promote the development of tumor diseases, but the mechanism of action of Nek9 in breast cancer is not clear yet." (PMID 35935324, 2022). "The expression levels of lncRNA ATB and Nek9 in breast cancer patients may be positively correlated with the development of the disease and closely correlated with lymphatic metastasis and TNM stage of breast cancer." (PMID 35935324, 2022).
melanoma (4 papers, 2018 to 2023). A malignant, usually aggressive tumor composed of atypical, neoplastic melanocytes. "Although the role of CDK16 has been explored previously in melanoma progression, little is known about how NEK9 expression impacts long‐term survival." (PMID 29112787, 2018). "Combined silencing of NEK9 and CDK16 was associated with enhanced inhibition of melanoma cell proliferation." (PMID 29112787, 2018). "In the TCGA melanoma cohort, the median overall survival (OS) for the low NEK9 expression group was 2.57 years (95% CI: 1.87, 5.68) compared to a median OS for the high NEK9 expression group of 1.98 years (95% CI: 1.27, 2.70)." (PMID 29112787, 2018). "Mechanistically, the silencing of NEK9 led to decreased phosphorylation of its downstream substrate CHK1 in WM1366 melanoma cells as well as the MIA PaCa‐2 KRAS‐mutant pancreatic cancer cell lines." (PMID 29112787, 2018). "Although NEK9 has been primarily associated with mitosis regulation, we did not observe any mitotic catastrophe in the melanoma cell lines following its silencing." (PMID 29112787, 2018). "Combined silencing of both CDK16 and NEK9 also led to a significant (P < 0.05) reduction in the growth of both 1205Lu and WM1366 melanoma cell lines." (PMID 29112787, 2018). "Both NEK9 and CDK16 were highly expressed in specimens of advanced melanoma, with high expression of both proteins correlating with a worse overall survival." (PMID 29112787, 2018). "For example, BRAF inhibitors were used in melanoma therapy, and MS-based chemical proteomics were used to identify never-in-mitosis-gene-A related kinase 9 (NEK9) and CDK16 as unique targets of dabrafenib." (PMID 36338621, 2022). "NEK9 and CDK16 were chosen for further study based upon their potent inhibition by dabrafenib in in vitro kinase assays, and by preliminary siRNA experiments in which their silencing inhibited the growth of NRAS‐mutant melanoma cells." (PMID 29112787, 2018). "siRNA‐mediated knockdown of NEK9 using siRNA pools from two manufacturers (siNEK9#1 and #2) reduced the growth of both BRAF‐mutant (1205Lu) and NRAS‐mutant (WM1366, IPC‐298, and M245) melanoma cell lines." (PMID 29112787, 2018). "The potential role of NEK9 in melanoma has not been previously explored." (PMID 29112787, 2018).
pancreatic cancer (4 papers, 2014 to 2021). "During our study of the expression of a Bcl2 mRNA variant in our Ela-mycPT1 mouse pancreatic cancer cell line, we serendipitously obtained a chimeric cDNA that was a fusion between the Bcl2 and the Nek9 genes." (PMID 27148738, 2016). "A similar gemcitabine hypersensitivity was observed following NEK9 knockdown in MIA PaCa-2 human pancreatic cancer cells and HeLa cervical cancer cells, indicating that gemcitabine hypersensitivity following NEK9 knockdown is not cell-type specific." (PMID 25217585, 2014). "In summary, we made the interesting observation that PRLR-SF signals induced via the NEK9-Hippo pathway reduce the expression of G6PD and TKT in the PPP and thereby reduce pancreatic tumor progression." (PMID 33664869, 2021).
arthrogryposis (3 papers, 2022 to 2024). A rare, non-progressive congenital disorder characterized by multiple joint contractures which are present at birth. "Our findings expand the genotype–phenotype knowledge of NEK9-associated arthrogryposis and provide evidence for further genetic counseling." (PMID 36712877, 2022). "In the present study, three novel variants of NEK9 associated with neonatal arthrogryposis were reported." (PMID 36712877, 2022). "Pathogenic missense variants in the NEK9 gene have previously been reported in individuals with arthrogryposis, avascular necrosis of the femoral head and cardiac defects, which was not consistent with the anomalies detected in our case." (PMID 35627109, 2022). "Our study expanded the clinical phenotype spectrum and gene spectrum of NEK9-associated arthrogryposis." (PMID 36712877, 2022). "Our findings expand the clinical phenotype spectrum and the gene spectrum of NEK9-associated arthrogryposis." (PMID 36712877, 2022). "Pathogenic variants in NEK9 were identified in the fetus with lethal congenital contracture syndrome 10 (OMIM: 617022) and in children with arthrogryposis, Perthes disease, and upward gaze palsy (APUG and OMIM: 614262)." (PMID 36712877, 2022).
colon cancer (3 papers, 2018 to 2024). "We here further investigated the relationship between NEK9 expression and well characterized clinicopathologic parameters related to a poor prognosis in colon cancer, i.e. N stage, M stage, LVI, PNI, and tumor budding and differentiation." (PMID 36611072, 2023). "In this study, we showed that high NEK9 expression could be an independent metastatic marker in colon cancer, and aberrant expression of the NEK9–EG5 axis had a role in microtubule assembly with acetylation during the tumorigenic process." (PMID 36611072, 2023). "In this study, we have demonstrated that NEK9 could be a factor for distant metastasis in patients with pT3 colon cancer." (PMID 36611072, 2023). "Moreover, the poor OS tendency in the high NEK9 group was also found in the M0 patient subgroup, indicating that NEK9 overexpression may have a crucial role in the onset of distant metastasis in colon cancer." (PMID 36611072, 2023). "NEK9 activates NEK6/7 and phosphorylates KIF11, playing an important role in spindle assembly, whereas an upregulated NEK9/KIF11 axis is related to the metastatic potential of colon cancer cells." (PMID 38672404, 2024). "Positive correlations were observed between NEK9 and EG5 or acetyl-α-tubulin (r = 0.236 and P = 0.007; r = 0.181 and P = 0.038, respectively) and concordant overexpression of the NEK9–EG5 axis was further confirmed in colon cancer cell lines." (PMID 36611072, 2023).
meningioma (3 papers, 2020 to 2021). A generally slow growing tumor attached to the dura mater. "NEK9 was associated with meningioma in a screening of all meningioma grades and normal meninges samples by LC-MS/MS." (PMID 32294979, 2020). "Furthermore, we were also able to monitor transitions for proteins like NEK9 and CKAP4 which have been reported to be associated with meningioma pathobiology." (PMID 32974197, 2020). "Peptides corresponding to NEK9, SELENBP1 which were previously reported as a marker for aggressivity via two independent proteomics study were also optimized and monitored across the meningioma patient cohort." (PMID 32974197, 2020). "NEK9 was shown to be up-regulated in grade I, II and III meningioma." (PMID 32294979, 2020).
ciliopathies (2 papers, 2022 to 2023). "Casey suggested that the lethal skeletal dysplasia caused by NEK9 mutation may represent a novel ciliopathy." (PMID 36712877, 2022). "Several NEK family members, including NEK8 and NEK9, span multiple functional categories, as NEK8 has been linked to cancer and cell cycle control and NEK9 has been implicated in ciliogenesis and ciliopathies." (PMID 37099601, 2023).
glioblastoma (2 papers, 2018 to 2022). The most malignant astrocytic tumor (WHO grade IV). "Significantly, Nek9 was also implicated in the survival of glioblastoma cells, with worse outcomes with high levels of Nek9 expression." (PMID 35409400, 2022). "NEK9 is also highly expressed in glioblastoma, with the potential to sensitize these tumors to chemotherapy by increasing sensitivity to DNA damage." (PMID 29112787, 2018).
glioma (2 papers, 2016 to 2018). A benign or malignant brain and spinal cord tumor that arises from glial cells (astrocytes, oligodendrocytes, ependymal cells). "NEK9 has been implicated in several cancers with increased expression being observed in recurrent glioma and imatinib‐resistant chronic myeloid leukemia (CML)." (PMID 29112787, 2018).
lung carcinoma (2 papers, 2023 to 2025). "LUSC AAF Sub-cohort: The activation of NIMA kinases (NEK9, NEK6, NEK7) pathway is closely linked to lung cancer cell cycle control, as these kinases regulate mitotic spindle formation and chromosomal stability, and their overexpression promotes proliferation, invasion, and poor prognosis in NSCLC." (PMID 41228248, 2025).
triple-negative breast carcinoma (2 papers, 2014 to 2021). An invasive breast carcinoma which is negative for expression of estrogen receptor (ER), progesterone receptor (PR), and human epidermal growth factor receptor 2 (HER2). "However, a low level of NEK9 mRNA is common in triple-negative breast cancers and is associated with poor overall survival and distant metastasis-free survival." (PMID 33664869, 2021). "Using a synthetic lethal screen of a RNAi library of nuclear enzymes to identify genes that when silenced cause gemcitabine sensitization or resistance in human triple-negative breast cancer cells, we identified NIMA (never in mitosis gene A)-related kinase 9 (NEK9) as a key component of the RSR." (PMID 25217585, 2014).
bladder carcinoma (1 paper, 2023). "Additionally, NEK6 and NEK9 both have negative correlations for patient survival outcomes in bladder carcinoma and positive correlations for patient survival outcomes in uterine corpus endometrial carcinoma." (PMID 37046733, 2023).
cardiomyopathy (1 paper, 2022). A disease of the heart muscle or myocardium proper. "CRISPR/Cas9-mediated disruption of NEK9 leads to cardiomyopathy in zebrafish." (PMID 36266340, 2022).
colorectal cancer (1 paper, 2025). A primary or metastatic malignant neoplasm that affects the colon or rectum. "FAM49B has been shown to promote proliferation and metastasis of colorectal cancer (CRC) by stabilizing MYC through phosphorylation of NEK9; however, its role in shaping the immune suppressive tumor microenvironment (TME), particularly in macrophage polarization, remains unclear." (PMID 41246334, 2025).
head and neck squamous cell carcinoma (1 paper, 2013). A squamous cell carcinoma that arises from any of the following anatomic sites: lip and oral cavity, nasal cavity, paranasal sinuses, pharynx, larynx, and salivary glands. "Interestingly, a recent proteomics study profiling kinase expression in drug-refractory head and neck squamous cell carcinoma identified a number of the same kinases (Lyn, MEK, NEK9) as we did in MYL-R cells, suggesting that these may represent a drug resistance kinome profile." (PMID 23826126, 2013).
heart failure (1 paper, 2022). Inability of the heart to pump blood at an adequate rate to meet tissue metabolic requirements. "Here, we observed that the transient or genetic loss of nek9 leads to heart failure and severely impaired cardiac contractility in zebrafish embryos." (PMID 36266340, 2022). "Loss of NEK9 is associated with heart failure and causally linked to ELC and cardiac contractility regulation." (PMID 36266340, 2022). "In addition to the induction of heart failure, the mutant nek9 alleles lead to early embryonic degradation." (PMID 36266340, 2022). "Heterozygous as well as compound heterozygous NEK9 transgenic zebrafish developed heart failure at the embryonic stage." (PMID 36266340, 2022). "The expressivity of the heart failure phenotype as reflected by fractional shortening was comparable between both lines (nek978del/+: vFS: 32.0 ± 5.1%, nek9+/500del vFS: 33.1 ± 4.1)." (PMID 36266340, 2022). "In detail, 38% of heterozygous nek978del/+ embryos showed impaired cardiac function, around 68% of heterozygous nek9+/500del embryos developed heart failure and 100% of analyzed compound heterozygous embryos (nek978del/500del) presented with the cardiac phenotype at 72 hpf." (PMID 36266340, 2022). "In heart failure, intracellular Ca2+ -levels are increased, which might stimulate the ELC kinase NEK9 as shown in this study in-vitro." (PMID 36266340, 2022). "Heterozygous embryos (nek978del/+ and nek9+/500del) can be occasionally raised to adulthood if heart failure is not severe and are available for line propagation." (PMID 36266340, 2022). "Transgenic nek9 zebrafish lines lacking the protein kinase domain develop the same heart failure phenotype indicating an essential role of NEK9 for cardiac function." (PMID 36266340, 2022).
lethal congenital contracture syndrome 10 (1 paper, 2021). "A study of one pedigree indicated that a recessive loss-of-function mutation in NEK9 (a missense mutation in the middle region) causes a lethal skeletal dysplasia (lethal congenital contracture syndrome 10; OMIM 609798), and patient fibroblasts showed a defect in primary cilia formation." (PMID 34078910, 2021).